INS (insulin)
Diseases named in the same sentence as INS in open-access papers (continued):
Sharing a sentence is not in itself a finding about the gene and the disease.
Obesity (continued). "E2-dependent protection against HFD-induced obesity is associated with increased physical activity and basal energy expenditure and improvements in systemic insulin sensitivity and glucose metabolism." (PMID 36387852, 2022). "Postprandial glucose and insulin dysregulation are independent risk factors for obesity and related cardio-metabolic diseases." (PMID 35458200, 2022). "In children with T2DM, childhood T2DM begins with reduced insulin sensitivity in skeletal muscle, adipose tissue and liver, and obesity is a major risk factor for reduced insulin sensitivity in children." (PMID 36324119, 2022). "In human white adipose tissue, ADIPINT expression is increased in obesity and linked to fat cell size, adipose insulin resistance, and pyruvate carboxylase activity." (PMID 35618718, 2022). "Next, we measured fasting plasma glucose and fasting plasma insulin levels in mice to assess the effect of engineered bacteria on obesity-associated insulin resistance." (PMID 35293806, 2022). "Bouchonville and colleagues tested the independent and combined effects of weight loss and exercise on insulin sensitivity and other cardiometabolic risk factors in frail, older adults with obesity." (PMID 35834023, 2022). "Of note in this context is that dopamine interacts with other neurotransmitter systems that have also been associated with obesity, such as the serotonin and opiate system, as well as with the neuroendocrine hormone insulin." (PMID 35448017, 2022). "Moderate weight loss improves insulin sensitivity and many of the frequent medical complications associated with obesity, such as type 2 diabetes." (PMID 35276970, 2022). "The defects in insulin signaling also affects the CNS, since obesity and T2D are clear risk factors for several pathologies related with the CSN, like AD and PD." (PMID 35406040, 2022). "The loss of miR-7 from Sim1 neurons induces severe obesity, increased energy intake, decreased energy expenditure, increased linear growth, and hyperinsulinemia due to increased insulin secretion." (PMID 36175420, 2022). "As we mentioned, several researches on PPARγ2 Pro12Ala polymorphism have indicated this polymorphism is pathogenic in different diseases including T2DM, insulin sensitivity, obesity, cardiovascular diseases, Alzheimer's disease, and cancer." (PMID 35547362, 2022). "In the context of T2D, it is widely accepted that pancreatic beta cells are exposed to a marked ER stress resulting from the increased insulin demand caused by hyperglycemia and obesity." (PMID 35629947, 2022). "CPT1 is involved in appetite regulation and insulin-mediated glucose and fatty acid metabolism, and its DNA methylation levels have been associated with a decreased risk of obesity." (PMID 35163268, 2022). "As has already been mentioned, our previous reports showed diminished levels of molecules associated with insulin signaling in endometria from women with obesity (plus IR) and PCOS." (PMID 35409282, 2022). "The clinical risk factors in individuals with WHR obesity presented an unfavorable trend as well: older, higher blood pressure, blood glucose, insulin, HOMA-IR, and 10-year cardiovascular risk score (P <0.0001)." (PMID 36387872, 2022). "MiR-150 is suggested as a miRNA which its deficiency is involved in the obesity-associated inflammation of adipose tissue and the resulting insulin resistance." (PMID 34751020, 2022). "The mechanism by which ADT is thought to increase CV risk is by decreasing insulin sensitivity and promoting dyslipidaemia and obesity, thus leading to an increased risk of CV morbidity and mortality." (PMID 36405935, 2022). "In contrast, oligomenorrhoea or amenorrhoea is also linked to obesity because obese adolescent females typically develop polycystic ovarian syndrome and hyperandrogenism, which is again fuelled by insulin resistance brought on by visceral adiposity." (PMID 36540483, 2022).
Obesity (continued). "Obesity is associated with a state of both insulin and leptin resistance, which in turn reduces the release of kisspeptin at the hypothalamus, resulting in the inhibition of gonadotropin secretion." (PMID 36009547, 2022). "The excessive accumulation of fat leads to dysregulation in secretion and metabolism of adipokines, including leptin and insulin which, thereby, develops obesity and associated complications." (PMID 36033946, 2022). "Both horses and donkeys can develop clinical issues associated with obesity; insulin dysregulation; and altered lipid metabolism, often termed equine metabolic syndrome or donkey metabolic syndrome, respectively." (PMID 36290132, 2022). "The abundance of Akkermansia muciniphila increases after RYGB, and this is negatively associated with obesity and positively associated with decreased inflammation and increased insulin sensitivity." (PMID 35328759, 2022). "These powerful effects of cold exposure on BAT glucose uptake are association with improved whole-body glucose disposal and insulin sensitivity in healthy or adults with obesity, or even in patients with T2DM." (PMID 36419097, 2022). "In another study in normal weight and obese children, Intestinibacter, among other genera, was associated with obesity and fasting insulin." (PMID 36144203, 2022). "Our previous work identified both OVX-induced overfeeding (positive energy imbalance) and obesity-associated metabolic dysfunction (peripheral insulin resistance) as important potential drivers of mammary tumor progression." (PMID 35725493, 2022). "The deficiency of DGAT1 in organisms promotes intestinal insulin release and alters lipid absorption, thus improving obesity and its adverse effects." (PMID 35845812, 2022). "We emphasised the cellular and physiological mechanisms underlying the effects of mushrooms on obesity and highlight the effects related to the variation of hormones that regulate satiety, adipocyte function, and insulin sensitivity." (PMID 35205965, 2022). "As obesity, visceral adiposity, and hepatic steatosis are associated with impaired glucose and insulin homeostasis, we subjected the mice to 16 h fasted OGTT after 12 weeks of HFD feeding." (PMID 36145123, 2022). "Obesity causes hyperinsulinemia that can drive tumor growth and reducing insulin levels in mouse models inhibits tumor growth." (PMID 35984550, 2022). "We found that gene expression of GHR, IGF-1 and IGFBP-3 was compromised in AT of children with overweight/obesity and was associated with parameters of adipocyte function such as adipocyte hypertrophy and increased fasting insulin levels." (PMID 36384443, 2022). "Some studies showed an association between good glycemic control and overweight/obesity probably related to insulin intensive treatment." (PMID 34983637, 2022). "The receptor for advanced glycation end products (RAGE) plays an important role in obesity-associated insulin sensitivity." (PMID 36348465, 2022). "Regarding metabolic variables, obesity was associated with an increase in fasting insulin levels, HOMA-IR, GOT, and uric acid, and a decrease in HDL-cholesterol levels." (PMID 35807162, 2022). "The activation of GPR81 receptors in adipose tissue leads to the inhibition of lipolysis in adipocytes, indicating a synergistic effect of lactate with insulin and its potential association with the development of obesity." (PMID 36230479, 2022). "Of this dysfunction, there are three common mechanisms related to obesity-associated cancer risk: impaired insulin and metabolic signaling, altered sex hormone metabolism, and dysregulated inflammatory conditions." (PMID 35870055, 2022). "In this context, research in late-onset obesity rats has reported truncation of mitochondrial assembly factors being associated with increased adiposity and dysregulated insulin signaling." (PMID 36067173, 2022).
Obesity (continued). "Adipokines are highly active biopeptides involved in glucose metabolism, insulin regulation and the development and progression of obesity and its associated diseases." (PMID 35872989, 2022). "Positive association was observed for leptin, CRP, fasting insulin, and estradiol, when comparing women with obesity or overweight versus normal weight." (PMID 35048536, 2022). "Exercise and weight loss are well known to improve insulin sensitivity and prevent obesity and subsequent metabolic syndrome." (PMID 35040046, 2022). "A study identified certain DNA methylation regions at birth that are linked to metabolic health like obesity or insulin sensitivity in later childhood." (PMID 36439251, 2022). "The authors suggest that individuals with high postprandial insulin have a chronic “brake” on lipid metabolism predisposing them to obesity." (PMID 35740478, 2022). "Its anabolic action promotes postnatal growth after weaning, however, chronically elevated insulin levels are associated with obesity and abnormal fat metabolism." (PMID 35025875, 2022). "Its accumulation during obesity is linked to tolerance observed toward insulin (Yazıcı and Sezer, 2017)." (PMID 35754463, 2022). "Equine metabolic syndrome (EMS) is characterised by obesity (either generalised or regional), insulin dysregulation (ID) and a predisposition to laminitis." (PMID 34713928, 2022). "Additional results describing the association of sarcopenic obesity using WHO thresholds for obesity (using BMI and waist circumference) with indices of insulin-glucose homeostasis are included in the Supplemental Appendix S2 in S1 File." (PMID 36490255, 2022). "Adverse perinatal outcomes linked to obesity have been associated with increased placental and systemic inflammation, oxidative stress, pre-pregnancy maternal insulin levels and hyperinsulinemia." (PMID 35348641, 2022). "Rs16835198 was found to be significantly associated with insulin sensitivity and obesity in the German and Egyptian populations, respectively." (PMID 36004352, 2022). "This in turn is caused by hormones involved in obesity, such as adipokines, glucocorticoids, and insulin, secreted in an abnormal fashion and acquire aberrant signaling promoting fat storage." (PMID 36591465, 2022). "Further, obesity has been associated with detrimental impacts on the muscle’s metabolic role in maintaining insulin sensitivity, regulating ectopic lipid deposition, and regulating energy balance." (PMID 36613864, 2022). "BMI, WC, adults with obesity, high glycemic diet, HbA1c, and fasting insulin levels maintained an independent association with HOMA-IR." (PMID 36570168, 2022). "Studies have reported that obesity is associated with inflammation that contributes to impaired insulin signaling in adipose tissue, liver tissue, and skeletal muscle." (PMID 35807667, 2022). "Among dietary interventions, fasting, calorie restriction and ketogenic diets (KD) have also been widely proposed to reverse obesity and T2D, being able not only to promote weight loss but also to enhance insulin sensitivity and reduce inflammation." (PMID 33967682, 2021). "MCP-1 is a member of the chemokine superfamily that functions in the recruitment and activation of monocytes during inflammation, which stimulates obesity-associated macrophage infiltration, and its gene expression is sensitive to insulin levels." (PMID 34571976, 2021). "In two obese mouse models, Ela functions as an effective compound in alleviating the clinical signs of obesity syndromes such as lowering glucose levels, inducing fat loss, and improving insulin sensitivity." (PMID 34671010, 2021). "Vitamin D deficiency, obesity and its comorbidities and particularly high levels of insulin, HOMA-IR, LDL cholesterol, and total cholesterol should be prevented among adolescents, and boys especially, to avoid the development of cardiovascular disease." (PMID 34653200, 2021).
Obesity (continued). "The high abundance of this bacterium in HFHS-fed mice has been associated with protection against obesity and an increase in insulin sensitivity." (PMID 34099716, 2021). "The single nucleotide polymorphism (SNP) rs17782313 near the MC4R gene has been linked to obesity, and a previous study using magnetoencephalography has shown that carriers of the mutant allele have decreased cerebrocortical response to insulin." (PMID 33806715, 2021). "Offspring display obesity or a higher body mass index in childhood and adulthood, impaired glucose and insulin tolerance in adulthood, and deficiencies in pancreatic beta-cell mass and function compared to offspring from uncomplicated pregnancies." (PMID 34828683, 2021). "In the context of obesity, insulin sensitivity in adipose tissue is impaired and is associated with macrophage infiltration and inflammation." (PMID 34177606, 2021). "A meta-analysis showed beneficial effects of a high-protein diet on several obesity and cardiometabolic parameters, including weight loss and fasting insulin." (PMID 33752703, 2021). "Among the main causes of elevated triglycerides in individuals with insulin sensitivity are obesity and adipose tissue dysfunction through mechanisms including chronic low-grade inflammation, increased lipolysis and altered adipocytokine production." (PMID 34731089, 2021). "AFABP-deficient mice displayed improved glycemia, insulin sensitivity and lipid metabolism in both dietary and genetically induced obesity, secondary to a reduced FFA efflux and increased glucose utilization in muscles." (PMID 33815359, 2021). "To address what kind of obesity-associated factors reduced the anticancer efficacy of AdipoRon, we examined the effect of glucose, insulin, IGF-1 and leptin on the survival of AdipoRon-treated Panc02-Luc-ZsGreen cells in vitro." (PMID 33536560, 2021). "Elevated glucose and/or insulin levels and altered liver function parameters are associated with overweight and obesity." (PMID 33034707, 2021). "At the same time, individuals with obesity with more social anxiety symptoms exhibit higher inflammation levels and greater insulin resistance, suggesting an increased susceptibility of the more anxious individuals to develop obesity." (PMID 34173157, 2021). "Pathological obesity‐associated FFAs contribute to hepatic insulin resistance by inhibiting insulin‐mediated suppressive effects on gluconeogenesis." (PMID 33520119, 2021). "Many studies have confirmed the numerous health benefits of aquatic aerobic exercise training, including reducing visceral fat, increasing insulin sensitivity, and alleviating obesity and metabolic diseases caused by obesity." (PMID 33437204, 2021). "In humans, GPNMB serum levels are associated and contribute to obesity and metabolic parameters such as hip circumference, body mass index and insulin resistance." (PMID 34608215, 2021). "Some authors suggest that adipose tissue-related oxidative stress causes the progression of MetS by interfering with insulin signal pathway transduction, which can be a major reason for obesity to be a proinflammatory state." (PMID 33440881, 2021). "Having less than 150 minutes of moderate intensity aerobic exercise per week has been reported to predispose to obesity and dyslipidemia, with resultant insulin resistance and cardiovascular deconditioning." (PMID 33493215, 2021). "IDO1 upregulation is a hallmark of obesity, and its deletion or inhibition improves insulin sensitivity, preserves the gut mucosal barrier, decreases chronic inflammation, and regulates lipid metabolism in liver and adipose tissues." (PMID 34473644, 2021). "Obesity is associated with IR, compensated by an increase in insulin production by β cell of pancreatic islets and the resulting hyperinsulinemia." (PMID 34208601, 2021).
Obesity (continued). "The brain is an insulin responsive tissue that is susceptible to inflammatory damage by kinases known to be increased by aging, and made worse by obesity, and which activate the brain’s immune cells, microglia." (PMID 33917279, 2021). "Obesity is associated with an increase in basal lipolysis and impaired insulin ability to suppress the FFA outflow." (PMID 34884217, 2021). "The sympathetic nervous system over-activation, stimulation of the renin–angiotensin–aldosterone system, alterations in adipose-derived cytokines, insulin resistance, and structural and functional renal changes are implicated in obesity–hypertension complex." (PMID 34442101, 2021). "While improving insulin sensitivity is likely to contribute to the decreased breast cancer risk, another important function of metformin in the context of obesity-associated breast cancer is its ability to inhibit aromatase expression in breast ASCs." (PMID 33859943, 2021). "Obesity is associated with high concentrations of circulating insulin and IGF-1 secreted from the pancreas and hepatic tissue." (PMID 33827616, 2021). "Fasn is involved in lipogenesis and associated with reduced insulin sensitivity and obesity, with expression increased by insulin within human adipocytes." (PMID 34938757, 2021). "Pathological myosteatosis in aging and obesity is associated with decreased insulin sensitivity and muscle mass and strength loss." (PMID 34676021, 2021). "CETP Taq1B polymorphism was found to be able to increase the association between dietary insulin indices and obesity." (PMID 34354158, 2021). "Neuroinflammation, represented by an increase in reactive glial cells and cytokine activation, was also found in the hypothalami of insulin-deficient rodents and those with high-fat (HF) diet-induced obesity and in obese humans." (PMID 34158075, 2021). "Obesity leads to adipose tissue becoming hypoxic, which causes imbalances in lipid metabolism, insulin resistance and local inflammatory responses, as well as capillary dysfunction and a decrease in the density of BAT." (PMID 34082784, 2021). "Obesity is associated with an imbalance of endocrine hormone signaling, especially impairments in insulin/IGF-1 pathway, decrease of adiponectin signaling, and leptin over-secretion and resistance." (PMID 33827616, 2021). "On the same line, evidence has also been achieved on the involvement of IRF5 in obesity-associated events such as fat accumulation, insulin resistance and polarization of macrophages toward an M1 proinflammatory phenotype." (PMID 33430520, 2021). "Complement activation is recognized in polycystic ovary syndrome (PCOS) to be associated with obesity and insulin sensitivity." (PMID 35250845, 2021). "In insulin-deficient conditions, the risk for obesity increases, and insulin uptake by the brain declines which leads to dementia." (PMID 34183987, 2021). "Supplementation with Omega-6 PUFAs indicated an increase in the AA levels in GDM which is associated with improved insulin sensitivity, glucose levels, and reducing obesity." (PMID 34130655, 2021). "Rates of overweight and obesity in T1D equal those of the general population, however, increased body weight and increased insulin demand are associated with more rapid disease progression after diagnosis of T1D in the 10–18 years age group." (PMID 34932928, 2021). "Although physiological levels of ROS are required for adipogenic differentiation and act as secondary messengers of the insulin signaling pathway and vasocontraction, excessive ROS have been shown to be a strong risk factor of obesity-related CVDs." (PMID 33748199, 2021). "The present study reports the molecular mechanisms underlying the anti-obesity and glucose-lowering effects of VS extract by regulating C/EBPα-mediated lipogenesis, PPARα-mediated fatty acid β-oxidation, and PPARγ-mediated insulin sensitivity." (PMID 33671428, 2021).